FXYD6P3 (FXYD domain containing ion transport regulator 6 pseudogene 3)
Synonyms: formerly FXYD8
Gene: Processed pseudogene on chromosome X (73,875,068 to 73,875,635, forward strand). Ensembl gene ENSG00000182707.
Subcellular location: Membrane